MIF (macrophage migration inhibitory factor)
Diseases named in the same sentence as MIF in open-access papers (continued):
Sharing a sentence is not in itself a finding about the gene and the disease.
laryngeal carcinoma (7 papers, 2013 to 2025). Carcinoma that arises from the laryngeal epithelium. "Finally, in laryngeal carcinoma, elevated MIF expression was associated with a worse prognosis in terms of local recurrence and cancer metastasis." (PMID 27788497, 2017). "GSEA was used to screen the pathways involved in MIF-regulating pathways in laryngeal cancer (gene sets enriched in phenotype l (251 samples))." (PMID 36042480, 2022). "Concerning MIF, it was observed that the increase in MIF expression induced a reduction in the number of CD3+ T cells in the stromal compartment of laryngeal carcinoma tissues." (PMID 30634708, 2019). "In this study we tested the relevance of tumoral MIF and of tumor-infiltrating neutrophils (CD66b-positive cells) for the survival of larynx carcinoma patients." (PMID 23409183, 2013). "Next, we investigated the relevance of AHNAK, MIF and CD66b taken in combination regarding survival of larynx carcinoma patients." (PMID 23409183, 2013). "In further studies we sought to confirm the relative values of AHNAK, MIF and CD66b as prognostic markers in larynx carcinoma by multivariate survival analysis using Cox regression model." (PMID 23409183, 2013). "Moreover, hypoxia also induces alterations in the lipid metabolism of laryngeal carcinoma cells through the upregulation of the macrophage migration inhibitory factor (MIF)/IL-6/JAK-STAT pathway." (PMID 40724877, 2025). "Thus, the MIF/IL-6/JAK/STAT pathway is expected to provide a new approach for the treatment of laryngeal cancer." (PMID 36042480, 2022). "Three genes, lactate dehydrogenase A (LDHA), enolase 2 (ENO2) and macrophage migration inhibitory factor (MIF), may be involved in lipid metabolism in laryngeal cancer cells." (PMID 36042480, 2022). "In further studies, we determined whether there might be a relationship between expression levels of AHNAK, MIF or CD66b and 5-years overall survival of larynx carcinoma patients." (PMID 23409183, 2013). "In addition, MIF plays a key role in disturbing lipid metabolism in laryngeal carcinoma." (PMID 40066443, 2025). "Moreover, this study showed that targeting lipid metabolism such as MIF might be a promising therapeutic option for the treatment of laryngeal cancer." (PMID 36042480, 2022). "Thus, our findings indicate that combined analysis of AHNAK with either MIF or CD66b might be a good strategy for an accurate prognosis in larynx carcinoma patients." (PMID 23409183, 2013). "Additionally, these findings suggest that AHNAK might 'cooperate' with MIF and/or neutrophils to enhance progression of larynx carcinoma." (PMID 23409183, 2013). "MIF, ENO2 and LDHA were identified to be related to lipid metabolism when laryngeal cancer cells were exposed to hypoxia, which is consistent with the RNA-seq analysis of Hep2 cells exposed to hypoxia." (PMID 36042480, 2022). "Implications for MIF in HNSCC have already been reported in several studies, which have established that MIF leads to cancer progression and poorer prognosis, notably in laryngeal carcinoma." (PMID 30634708, 2019).
leishmaniasis (7 papers, 2013 to 2024). Infectious disease that is transmitted through the bite of hematophagous female phlebotomine sand flies. "Mice that lack MIF are more susceptible to leishmaniasis and cysticercosis and in vivo administration of recombinant MIF reduced the severity of Leishmania major pathogenesis in mice." (PMID 33621237, 2021). "Understanding of the role of host MIF during leishmaniasis is confounded by the existence of parasite-encoded MIF orthologs that are produced by many species of Leishmania during infection." (PMID 32244916, 2020). "With this in mind Leishmania MIF should be viewed as a promising target for immunization and pharmacologic inhibition in an effort to develop effective strategies for combating leishmaniasis." (PMID 32244916, 2020). "While the impact of host MIF on experimental L. major infection in mice has been well characterized, the impact of the cytokine in human leishmaniasis is less well understood." (PMID 32244916, 2020). "Low expression of MIF has been described as favoring infection and disease progression in leishmaniasis." (PMID 28827791, 2017). "Thus, development and testing of Leishmania MIF inhibitors may prove an effective strategy for targeted treatment of leishmaniasis." (PMID 32244916, 2020). "However, in humans MIF has not been shown to have a protective effect during leishmaniasis and may in fact be detrimental." (PMID 32244916, 2020).
liver disease (7 papers, 2015 to 2023). "The immunomodulatory effect of MIF after a liver injury has been reported in many liver diseases." (PMID 37102665, 2023). "Furthermore, MIF is a proinflammatory factor that mediates inflammatory liver damage in different liver diseases." (PMID 37102665, 2023). "Taken together, the complex biology of MIF in liver diseases is multifaceted and context dependent." (PMID 33945507, 2021). "Furthermore, there are some first indications that MIF may contribute to development of diet-induced hepatic steatosis in NAFLD, while observations in advanced liver disease are conflicting, describing both pro- and anti-fibrotic effects of MIF." (PMID 26124760, 2015). "What is even more compelling about hepatocyte-derived MIF controlling chemokine expression is that hepatocytes are a pivotal source of many chemokines, like CCL2 and the IL-8 family, in liver diseases, including AH." (PMID 33945507, 2021). "MIF elicits detrimental effects at specific phases and models of liver disease, and studies have raised that MIF contributes to ethanol-induced hepatocyte damage; however, none have reported on how MIF reacts under hepatic lipotoxicity." (PMID 36147562, 2022).
pneumonia (7 papers, 2009 to 2023). An acute, acute and chronic, or chronic inflammation focally or diffusely affecting the lung parenchyma, caused by an infection in one or both of the lungs (by bacteria, viruses, fungi, or mycoplasma.). "There are reported associations between high‐expression MIF alleles and improved outcomes in pneumonia and meningococcal meningitis." (PMID 32705792, 2020). "However, the levels of CTACK, Eotaxin, IL-16, macrophage migration inhibitory factor (MIF), and MCP-1 in the pneumonia group were significantly lower than those in the bronchitis group." (PMID 36119044, 2022).
pulmonary tuberculosis (7 papers, 2013 to 2021). A bacterial infection that affects the lungs and is caused by Mycobacterium tuberculosis. "The objective of this study was to evaluate, in a case-control study, the association between MIF -173 G>C single nucleotide polymorphism (SNP) and susceptibility to pulmonary TB in a population of southern Brazil." (PMID 32525926, 2020). "Further studies, including patients from various regions of Brazil are necessary to better evaluate the association between MIF -173 G>C polymorphism and susceptibility to pulmonary TB." (PMID 32525926, 2020). "The objective of this study was to evaluate the association between macrophage migration inhibitory factor (MIF) -173 G>C single nucleotide polymorphism (SNP) and susceptibility to pulmonary TB in a population of southern Brazil." (PMID 32525926, 2020). "In spite of these concerns, this is the first study to evaluate the association between MIF -173 G>C polymorphism and susceptibility to pulmonary TB in Brazil." (PMID 32525926, 2020). "Many studies have indicated that Macrophage migration inhibitory factor (MIF)-173G/C gene polymorphisms are associated with susceptibility to pulmonary tuberculosis (PTB)." (PMID 28331211, 2017). "The aim of this study was to evaluate the possible association between MIF -173 G/C functional polymorphism and pulmonary tuberculosis (PTB) in an Iranian population from Zahedan Southeast Iran." (PMID 27065766, 2015). "Furthermore, serum levels of MIF were reported to be a useful marker for assessing the effects of therapy in active pulmonary tuberculosis (APTB) patients." (PMID 30841876, 2019). "Furthermore, significantly higher MIF concentrations were observed in patients with pulmonary tuberculosis (PTB) than in the healthy population." (PMID 28331211, 2017). "The mean serum concentration of MIF in the CCC group was 20.9 ng/ml, which is comparable with the level reported previously in patients with pulmonary tuberculosis (mean of 19.8 ng/ml)." (PMID 23451183, 2013).
rhabdomyosarcoma (7 papers, 2013 to 2025). A rare aggressive malignant mesenchymal neoplasm arising from skeletal muscle. "In rhabdomyosarcoma, MIF knock-out increased the potential of cellular immune interventions." (PMID 39908652, 2025).
schizophrenia (7 papers, 2013 to 2024). A major psychotic disorder characterized by abnormalities in the perception or expression of reality. "The serum MIF level and microsatellites/single nucleotide polymorphisms (SNPs) in the MIF gene promoter region are known to be associated with schizophrenia (SCZ)." (PMID 35324982, 2022). "The analytes showing the largest ratiometric differences included ferritin, macrophage migration inhibitory factor, carcinoembryonic antigen and haptoglobin, which were all more than 1.5-fold higher in schizophrenia patients compared to controls." (PMID 24244349, 2013). "Several studies have also identified MIF level as a potential biomarker for schizophrenia." (PMID 38531873, 2024). "Additionally, a study of biomarkers for early detection of schizophrenia reported significantly altered levels of plasma MIF in a panel of blood-based biomarkers." (PMID 30976114, 2019).
Shock (7 papers, 2009 to 2017). The state in which profound and widespread reduction of effective tissue perfusion leads first to reversible, and then if prolonged, to irreversible cellular injury. "In the present study, we show first evidence of the effect of lowering MIF levels in patients undergoing CRRT in septic shock." (PMID 27313864, 2016). "The AI group had significantly more septic shock patients and higher prothrombin time ratios, serum MIF, and baseline cortisol than did the NAR group (P < 0.05)." (PMID 20021698, 2009). "Here, we provide a model illustrating that autophagy mediates the disorganization and degradation of junction proteins in MIF-induced vascular leakage, which is in agreement with the “rapid and reversible” features of vascular leakage in acute inflammatory shock patients." (PMID 25617421, 2015).
skin cancer (7 papers, 2010 to 2024). "Bulk-RNA sequencing of patient tumor samples from the Skin Cancer SPORE Biorepository was used to evaluate for differential gene expression of MIF, DDT, CD74, and selected inflammatory markers, and gene expression was correlated with patient survival outcomes." (PMID 39028303, 2024). "Our group surprisingly classified MIF as a functional tumor suppressor in chemically-induced skin cancer models." (PMID 37464010, 2023). "Interesting but sometimes contradictory findings were made in previous studies on the roles of MIF and D-DT in skin tumors." (PMID 37464010, 2023). "For example, MIF expression is increased in inflammatory skin diseases such as alopecia areata and skin tumors and MIF orthologs are produced by Leishmania spp." (PMID 29487601, 2018). "This article reviews the latest findings on the roles of MIF with regard to UV-induced skin cancer." (PMID 24281172, 2010). "In skin cancer models of WT, P1G-MIF, and MIF knockout mice revealed that the P1G-MIF group (lacking tautomerase activity and binding to CD74) displayed intermediate tumor incidence between the WT and knockout groups." (PMID 37880655, 2023). "We speculate that MIF may be an indicator of skin cancer, meaning that it does not appear in large quantities in the blood of healthy people." (PMID 35209841, 2022). "Interestingly, MIF and D-DT do not appear to have a major effect on chemically-induced skin tumors, which may be due to increased tumor immunity in chemical carcinogenesis." (PMID 37464010, 2023).
thyroid (7 papers, 2014 to 2024). "Using Spearman’s rank correlation analysis, we analyzed the correlation between preoperative serum MIF levels and surgical difficulty factors, including TDS, operation time, and blood loss in patients with thyroiditis." (PMID 34575145, 2021). "Some of miR-451 downstream targets are well known to be involved in the control of invasive properties of thyroid and others cancers: MIF and PSMB8." (PMID 32824921, 2020). "Some studies have shown that MIF is thought to be involved in thyroid diseases." (PMID 34575145, 2021). "However, the relationship between the severity of thyroiditis and serum level of MIF requires further investigation." (PMID 34575145, 2021). "We speculate that the serum level of MIF may be a predictor of the inflammatory status of thyroid diseases." (PMID 34575145, 2021). "In the present study, we firstly found that MIF mRNA and protein expressions positively correlated with TPOAb and TgAb titers in HT patients, further supporting a close relationship between MIF and thyroid autoimmune response." (PMID 25861163, 2015). "We suggest that MIF may trigger the destruction of thyroid tissue at the later stage of the thyroiditis." (PMID 25506398, 2014). "Thus, the interaction CD74/MIF in AITD could contribute to opposed processes: exacerbation of thyroid infiltration by immune cells (especially in HT) and promotion of autocrine TFC repair in GD, as demonstrated in IBD intestinal mucosa and in skin epithelium wound healing." (PMID 39003267, 2024).
triple-negative breast carcinoma (7 papers, 2016 to 2026). An invasive breast carcinoma which is negative for expression of estrogen receptor (ER), progesterone receptor (PR), and human epidermal growth factor receptor 2 (HER2). "Inhibition of autophagy in triple-negative breast cancer (TNBC) has been shown to promote ROS-dependent macrophage migration inhibitory factor (MIF) secretion and stimulate M1 polarization." (PMID 39430253, 2024). "Overexpression of MIF has also correlated with worse survival in triple-negative breast cancer compared to other hormonal status." (PMID 35012533, 2022). "Lately, MIF has been described as a novel therapeutic target against metastatic triple-negative breast cancer (TNBC)." (PMID 34157052, 2021). "Furthermore, autophagy inhibition with CQ also induced the secretion of pro-inflammatory cytokines MIF (Macrophage migration inhibitory factor) and IL-6 in triple-negative breast cancer cells." (PMID 34706732, 2021). "More recently, another small-molecule MIF inhibitor, CPSI-1306, was shown to suppress tumor growth in triple-negative breast cancer models by inducing tumor cell apoptosis by downregulating survival and proliferation pathways." (PMID 41597203, 2026).
acute myeloid leukemia (6 papers, 2016 to 2025). Acute myeloid leukemia (AML) is a group of neoplasms arising from precursor cells committed to the myeloid cell-line differentiation. "Antibodies/inhibitors targeting CD33 and MIF were originally tested in clinical trials for the treatment of acute myelogenous leukemia (AML) or solid tumors." (PMID 28005991, 2016). "Delving deeper into the mechanisms of non-remission post-chemotherapy, our differential analysis revealed that specific pathways, including CCL, IFN-II, GALECTIN, and MIF, witness heightened expression in non-remission acute myeloid leukemia after chemotherapy." (PMID 37891580, 2023).
alopecia areata (6 papers, 2010 to 2026). Loss of scalp and body hair involving microscopically inflammatory patchy areas. "MIF-173 C allele polymorphisms carry a higher risk of vulnerability to the expansive types of alopecia areata." (PMID 40445486, 2025). "MIF is expressed in hair follicles, and there is a close association between reduced MIF in hair follicles and the development of alopecia areata, which is an autoimmune disease of the skin." (PMID 32481584, 2020). "Given this, MIF has been involved in the etiopathogenesis of the severe forms of alopecia areata." (PMID 40445486, 2025). "MIF is a cytokine produced by lymphocytes and peripheral blood mononuclear cell that may play a key role in the pathogenesis of extensive alopecia areata." (PMID 20300578, 2010). "Given the fact that antibodies against MIF have shown encouraging results in the treatment of murine hepatitis, MIF production control may show promise for effective treatment modalities in extensive alopecia areata patients." (PMID 20300578, 2010). "MIF levels are significantly elevated in alopecia areata patients." (PMID 20300578, 2010). "Furthermore, serum MIF levels were higher in patients suffering from extensive alopecia areata." (PMID 40445486, 2025).
Anxiety (6 papers, 2021 to 2024). Intense feelings of nervousness, tension, or panic often arise in response to interpersonal stresses. "A genetic study in the adolescent group revealed the association of MIF polymorphisms with anxiety and attenuated cortisol reactivity." (PMID 34575175, 2021). "To further explore the role of MIF within EPC-CM to neuronal repair in BICAL rats, we conducted a series of behavioral assessments, including cognition, locomotor activity and anxiety in the BICAL rats." (PMID 39543689, 2024).
cervical adenocarcinoma (6 papers, 2018 to 2024). An adenocarcinoma arising from the cervical epithelium. "It has been reported that MIF could promote cell growth in some diseases, such as cervical adenocarcinoma or neural stem/progenitor cells." (PMID 33148606, 2020).
chronic lung disease (6 papers, 2018 to 2024). According to the definitions of the American and British Thoracic Societies, including pulmonary functional tests, X-rays, and CT scans for items such as fibrosis, bronchiectasis, bullae, emphysema, nodular or lymphomatous abnormalities. "The macrophage migration inhibitory factor (MIF) is a pleiotropic cytokine that has been associated with chronic lung diseases." (PMID 38145300, 2024). "The capacity of cigarette smoke to alter MIF expression and the susceptibility to suffer from human chronic lung diseases has been proven, and in the murine model, chronic cigarette smoke exposure resulted in decreased MIF mRNA and protein expression in the intact lung." (PMID 32705792, 2020). "MIF’s role in the pathogenesis of PAH, induced by chronic hypoxia, or associated with chronic lung diseases, or idiopathic, has been explored in many studies." (PMID 30083544, 2018). "The WISP1-induced expression of MIF and relevant specific signaling pathways may be proven to be excellent candidates as novel targets to control inflammation in chronic lung diseases." (PMID 38145300, 2024). "The specific signaling pathways involved in WISP1-induced expression of MIF may prove to be excellent candidates for novel targets to control inflammation in chronic lung diseases." (PMID 38145300, 2024). "Based on our current knowledge on various causes and effects of MIF expression, it is currently unclear whether increasing or decreasing MIF expression as a therapeutic strategy would be beneficial for COPD or other chronic lung diseases." (PMID 33046825, 2020).